CDKN2A (cyclin dependent kinase inhibitor 2A)
Diseases named in the same sentence as CDKN2A in open-access papers (continued):
Sharing a sentence is not in itself a finding about the gene and the disease.
cancer (continued). "CDKN2A encodes for p16INK4a, a protein that acts as a tumor suppressor gene and is involved in the modulation of cell cycle progression, thus explaining why CDKN2A deletion is a frequent event in cancer establishment." (PMID 35409194, 2022). "Among 6 up-regulated cancer driver genes, 4 genes encode proteins known to function as negative regulators of cell proliferation (CDKN2A); inducers of apoptosis (BAX); tumor suppressor (RPL22); inhibitors of transactivation of insulin promoter by recruiting a repressor complex (SPOP)." (PMID 36879662, 2022). "Thus, mutation and homozygous deletion of CDKN2A make it an adverse prognostic factor in a variety of cancers, which is in line with our result." (PMID 36203594, 2022). "Cancer stage, stage N, and stage T were closely associated with risk score and CDKN2A." (PMID 35321516, 2022). "Laboratory data suggest that cancer cells with loss-of-function alterations of CDKN2A may be sensitive to CDK4/6 inhibitors such as Palbociclib, Ribociclib, and Abemaciclib." (PMID 36140642, 2022). "Somatic mutations of CDKN2A are found in various sporadic forms of cancers." (PMID 35123577, 2022). "Two‐hit inactivation of CDKN2A/2B was frequently found in KRAS‐mutant LUAD in The Cancer Genome Atlas (TCGA) database, and loss of CDKN2A/B fostered cellular proliferation, cancer cell differentiation, and metastatic behavior in genetically engineered mouse models of KRAS‐mutant lung tumorigenesis." (PMID 35253368, 2022). "Inhibitors of CDK, termed cyclin-dependent kinase inhibitors (CKIs), regulate CDK activity and decreased expression of these regulatory proteins is frequently observed in many cancers, with p16, which is encoded by the gene CDKN2A, being the most well characterized CKI." (PMID 35936751, 2022). "The CDKN2A locus, also known as INK4A/ARF locus alternatively encodes two tumor suppressor proteins, p16INK4A and p14ARF (p19Arf in mice), and is one of the most frequently mutated genes in human cancers." (PMID 36605591, 2022). "Germline testing of 156 cancer related genes showed CDKN2A (c.301G>T) pathogenic mutation." (PMID 35123577, 2022). "CDKN2A could induce cell cycle arrest in G1 and G2 phases, and CDKN2A loss has been shown to be a significant event in several cancer types." (PMID 33952272, 2021). "CDKN2A may serve as a promising prognostic biomarker and is associated with immune infiltrates across cancers." (PMID 35004697, 2021). "Silencing of the CDKN2A tumor suppressor gene is causally associated with several cancer types." (PMID 33778063, 2021). "The CDKN2A gene encodes for two distinct tumor suppressor proteins, p16INK4A and p14ARF, however, the independent association of germline alterations affecting these two proteins with cancer is under-appreciated." (PMID 33766116, 2021). "However, patients with CDKN2A mutations showed significantly shorter OS (HR: 1.72, 95% CI: 1.34–2.21, p < 0.001) after adjusting for cancer type, age at diagnosis, and sex." (PMID 34204917, 2021). "Therefore, the study of CDKN2A gene is very important to further understand the impact of gene mutation on the development of cancer." (PMID 35004697, 2021).
cancer (continued). "A number of these genes are not only known to be involved in the predisposition of several cancers (CDKN2A, POT1, FHIT) but are also associated with immune traits (monocyte, platelet, etc.), cholesterol, high density lipids/light density lipids, and allergens in humans." (PMID 33793571, 2021). "Cyclin-dependent kinase inhibitor 2A (CDKN2A) encodes and results in a production of p16 genes that are involved with a range of cellular pathways which consists of suppression of the cancer cell cycle, cell senescence, apoptosis, differentiation, and DNA repair." (PMID 33896386, 2021). "Collectively, these observed trends imply that CDKN2A-associated cancer susceptibility could be dependent on molecular consequence of the variant and affected transcript." (PMID 33766116, 2021). "However, in contrast to Cdkn1 genes, Cdkn2a/b is one of the most frequently mutated gene loci in human cancer, suggesting a crucial function of these genes in maintaining genomic stability of quiescent cells." (PMID 33078209, 2021). "Loss of CDKN2A/p16 may also play a role in progression to cancer in IPMNs as it is a common finding in MCNs with HGD but is absent in MCNs with LGD." (PMID 33808853, 2021). "Additionally, homologous deletion or loss of heterozygosity on the CDKN2a locus has also been frequently reported in numerous cancers, including breast, bladder, liver, lung, oral, prostate, and kidney cancer." (PMID 32759846, 2020). "These additional cancer risks are not consistently observed, however, and this may indicate that the risk of other cancer types reflects the specific germline CDKN2A mutation." (PMID 33076392, 2020). "We analysed a total of seven different Cdkn2a-deficient RT2-cancer cell lines in vitro." (PMID 32165639, 2020). "MTAP loss often occurs with p16INK4a/CDKN2A deletion, which is prevalent in cancer." (PMID 32824193, 2020). "The loss of function due to methylation or deletion of CDKN2A has been observed in many cancers." (PMID 33066747, 2020). "Somatic mutations in CDKN2A are common in the majority of human cancers." (PMID 32670354, 2020). "Also, loss of cell cycle controlling gene CDKN2A, another commonly deleted gene in cancer, can break glucose equilibrium and cause increased insulin secretion by pancreatic β cells." (PMID 31313989, 2019). "However, recent Cancer Genome Atlas project analysis indicated that CDKN2A gene (encoding p16 protein) is often deleted or mutated in smoking related HNSCC cancers." (PMID 30707715, 2019). "Many of the genes exhibiting higher H3K27me2/3, which can span large chromatin regions, are cancer-associated and include cyclin-dependent kinase inhibitor 2A (CDKN2A) encoding the tumor suppressor p16/INK4A and cell cycle regulator Cyclin-dependent kinase 6 (CDK6)." (PMID 31086012, 2019). "The CDKN2A/B genomic locus is associated with risk of human cancers and metabolic disease." (PMID 30087655, 2018). "Furthermore, all patients with homozygous deletions of CDKN2A/B also harbored other cancer-related mutations." (PMID 29463802, 2018). "Regardless of its role in tumorigenesis of the MNTI, it is probable that the germline D74A CDKN2A mutation may also predispose patients to an increased risk of developing other cancers later in life." (PMID 27519597, 2016). "However, our results, taken together with what found by Ter-Minassian and colleagues convincingly suggest that the pleiotropic CDKN2A region is associated with the risk of developing PNETs as already observed for several other cancer types." (PMID 28008994, 2016).
cancer (continued). "TGX221 also targeted cancer cells with CDKN2A and PTEN mutations." (PMID 25853938, 2015). "We reasoned that like other dominantly heritable cancers, CDKN2A mutations carried in phenotypically normal SFs from FM patients could provide clues to the early molecular events that predispose FM melanocytes to malignant conversion." (PMID 23371019, 2013). "ARF is one product of the Cdkn2a locus, a site of frequent mutations in human cancer." (PMID 22860046, 2012). "Interestingly, the gene encoding p15 (CDKN2B) maps to the same chromosomal region as CDKN2A, and so deletions present in cancer cells involving CDKN2A often also affect CDKN2B, resulting in functional loss of both p16 and p15." (PMID 21052502, 2011). "However, this pan-cancer analysis revealed that CDKN2A could be a potential diagnostic and prognostic biomarker primarily in COAD." (PMID 38894777, 2024). "However, the exact mechanism by which CDKN2A causes poor prognosis in cancer is still unclear." (PMID 37723477, 2023). "However, although all these pathologies (including cancers) represent the major causes of death and CDKN2A altered expression is indubitably associated with these disorders, the molecular connections between CDKN2A function and clinical conditions still need to be clarified." (PMID 35456025, 2022). "Two recent studies correlated CDKN2A/MTAP loss as an ICT resistance marker in several pan cancers but were limited by the small number of HPV– HNSC patients and could not evaluate the contributions and interactions of other chromosomal sites or genes to this observation." (PMID 36395141, 2022). "In addition, CDKN2A is also frequently somatically mutated in various cancers." (PMID 34454516, 2021). "CDKN2A is another frequently mutated gene in MPM, and is located <1Mb from several interferon genes raising the possibility that prognostically significant loss of IFN gene expression may reflect a “passive hitchhiking event” associated with CDKN2A deletion in cancer." (PMID 34178677, 2021). "Moreover, mutations of RAS, BRAF, MEK1, and MEK2 could cooperate with CDKN2A loss in different cancers." (PMID 33807122, 2021). "Therefore, the development of cancer is often accompanied by CDKN2A mutations; the loss of its anticancer function may promote the neoplastic transformation of cells, subsequently inducing proliferation, invasion, and metastasis." (PMID 32420374, 2020). "We then evaluated if there was any alteration in some of the principal effectors of this axis commonly deregulated in cancer (RB, E2F, CDKN2A, CCDN1, CDK4) by amplification, deletion, or mutation that could be associated with the expression pattern of the lncRNA22." (PMID 31934613, 2020). "However, the Chi-squared test χ2 revealed, after exclusion of gender-specific cancer diseases, five different genetic mutations that are significantly more common in men than in women: CDKN2A (p = 0.04), CTNNB1 (p = 0.002), KIT (p = 0.0005), SLX4 (p = 0.034), and VHL (p = 0.046)." (PMID 33114048, 2020). "Indeed, CDKN2A status was found to be associated with various cancers." (PMID 30555633, 2018).
cancer (continued). "Germline variants affecting regulation of CDKN2A may alter the balance between proliferation and senescence in specific tissues, thereby leading to an increased risk of developing OS and potentially also other cancers in adolescence and adulthood." (PMID 24330828, 2013). "This increase in expression (particularly of CDKN2A) is associated with the impaired regenerative potential of several tissues observed during aging; however, CDKN2A/B is silenced or deleted in a wide-range of human cancers, suggesting it has a key role preventing cancerogenesis." (PMID 23306151, 2013). "Homozygous deletion of MTAP occurs in approximately 15% of all human cancers due to its chromosomal proximity to the CDKN2A/B locus." (PMID 41825704, 2026). "In cancer, the typical epigenetic patterns are altered, leading to the activation of anti-apoptotic and pro-proliferative genes while silencing TSGs such as CDKN2A (Cyclin-Dependent Kinase Inhibitor 2A)." (PMID 40650308, 2025). "Genes such as FDX1, CAT, CDKN2A, DLAT, LIPT1, and COMMD1, which are associated with cuproptosis, are crucial for the growth, advancement, and spread of various cancers." (PMID 40109870, 2025). "Pan-cancer analysis has revealed that cuproptosis related genes, such as ATP7B, ATP7A, and CDKN2A, harbor high-frequency mutations or abnormal expression patterns in various types of cancer." (PMID 40406488, 2025). "MTAP is a gene adjacent to CDKN2A on chromosome 9p and is frequently co-deleted with CDKN2A in a wide range of cancers." (PMID 40361368, 2025). "Further quantitative assessment corroborated this finding, indicating that the proportion of CDKN2A positive expression in cancer tissues was substantially elevated relative to normal tissues." (PMID 39895793, 2025). "ANRIL is a large antisense non-coding RNA gene (126-kb region, consisting of 19–21 exons) with the first exon located in the promoter region of CDKN2A, regulating cancer progression through epigenetic silencing of other genes in this cluster." (PMID 40046620, 2025). "We were also able to determine the functional classification of CDKN2A missense somatic mutations in COSMIC, TCGA, JHU, and MSK-IMAPCT by cancer type." (PMID 38234851, 2025). "CDKN2A/B, crucial in the regulation of the cell cycle, are frequently lost in cancer, particularly in CM." (PMID 40756116, 2025). "Monophasic tumors are characterized by higher expression of cancer-related genes CDKN2A, EGFR, and PDGFRL, which can be considered as potential targets for treatment." (PMID 41155410, 2025). "Inactivation of retinoblastoma protein (Rb) and cyclin-dependent kinase inhibitor 2A (CDKN2A) occurs frequently in cancer." (PMID 40245079, 2025).
cancer (continued). "MTAP is often homozygously deleted as a consequence of a passenger event, in which neighbor gene cyclin-dependent kinase inhibitor 2A (CDKN2A) is deleted, with a frequency of approximately 15% in cases of pan-cancer and exceeding 50% in certain cancer types." (PMID 40590219, 2025). "Apart from the more immunosuppressive microenvironment, monophasic tumors are characterized by higher expression of cancer-related genes CDKN2A, EGFR, and PDGFRL, which can be considered as potential targets for treatment." (PMID 41155410, 2025). "The tumor suppressor p16INK4a, encoded by CDKN2A, is frequently inactivated in cancer through genetic or epigenetic mechanisms." (PMID 40649906, 2025). "Hypermethylation of the CDKN2AINK4a promoter, the most frequently described epigenetic aberration of CDKN2A, has been found to silence CDKN2A in various cancer types." (PMID 40649906, 2025). "We found elevated expression of CDKN2A (coding for p14/p16) in MSCs compared to cancer cells and iPSC lines." (PMID 39621192, 2025). "This novel method provides a valuable tool for future studies seeking a deeper understanding of CDKN2A regulation in cancer." (PMID 40649906, 2025). "Considering that the incidences of MTAP and CDKN2A/B co-deletion are events affecting 15% of cancers, MTAP has a high potential of being exploited for targeted therapy." (PMID 41439984, 2025). "While CDKN2A deletions were enriched in RBness cancers, conversely, amplifications in CDKN2A were enriched in RB1-defective cancers." (PMID 40138429, 2025). "The MTAP gene is located at 9p21.3, only 30 kb apart from the cyclin dependent kinase inhibitor 2A (CDKN2A) gene which is homozygous deleted in up to 15% of all human cancers." (PMID 39668577, 2025). "Genes like HRAS, CCND1, and CDKN2A are well-known drivers of cancer-related processes, including cell cycle progression, and apoptosis." (PMID 40333905, 2025). "The CDKN2A gene is situated on chromosome 9p21.3, a region known for its involvement in tumorigenesis across different cancer types." (PMID 39925808, 2025). "Previous studies have shown that CDKN2A promoter methylation plays a key role in cancer and is a potential biomarker for cancer prognosis." (PMID 40065477, 2025). "For this, we used an MTAP/CDKN2B-AS1 deletion (MA-del) assay to examine various EJ outcomes via the chromosomal deletion rearrangement of the CDKN2A gene, a common deletion rearrangement found in various cancer types 51,52." (PMID 41285797, 2025). "Cyclin-dependent kinase inhibitor 2 A (CDKN2A) is a protein functions in inhibiting cancer, which also controls the G1-S phase transition in cell cycle, which thereby regulates cell growth." (PMID 40855044, 2025). "However, in other cancers, the loss or low expression of CDKN2A may indicate a worse prognosis." (PMID 40861807, 2025). "For example, MTAP (encoding methylthioadenosine phosphorylase) is located in proximity to the tumor suppressor gene CDKN2A in the genome and thus often co-deleted with CDKN2A in cancer cells." (PMID 38638566, 2024). "As expected, CDKN2A gene expression as a tumor suppressor gene in both types of cancer increased significantly after treatment which can be aligned with palbociclib in proliferation inhibition." (PMID 39116089, 2024). "Normal skin rarely shows CDKN2A point mutations, which were frequent drivers in cSCC, suggesting that CDKN2A inactivation appears to be specific to cancer clones." (PMID 39200957, 2024).